IL6 (interleukin 6)
Diseases named in the same sentence as IL6 in open-access papers (continued):
Sharing a sentence is not in itself a finding about the gene and the disease.
intestinal infection (17 papers, 2013 to 2025). "IL-6 neutralization in mice after intestinal infection with Yersinia, caused a dramatic decrease in local and circulating IL-1ra, suggesting that the pro-inflammatory IL-6 interplays with IL-1 indirectly via IL-1ra." (PMID 23472217, 2013). "The challenge of healthy adult male volunteers with attenuated ETEC prevented intestinal infection upon a secondary challenge with the same bacteria, and this protective effect was associated with improved productions of TNF-α and IL-6 by blood monocytes." (PMID 40141330, 2025). "In this study, CEO decreased the cytokines IL-6, IL-8, and IL-17A, which were elevated by intestinal infection, and improved inflammatory status." (PMID 40509258, 2025). "In intestinal infections such as salmonellosis, there is an increase in IL-6 and IFN-γ levels, which stimulates an inflamed environment favorable to Salmonella multiplication and pathogenicity but impairs components of the indigenous microbiota." (PMID 30564201, 2018). "Gastrointestinal infections may upregulate IL-6 and IL-1β genes, therefore enhancing the permeability of the gastrointestinal epithelial cells." (PMID 41383965, 2025). "The inflammatory factors IL-6 and IL-8 were analyzed, as were pharmacodynamic indicators, to explore the effect of CEO on intestinal infection by C. albicans." (PMID 40509258, 2025). "In the situation of intestinal infection, JNK inhibition resulted in reductions of c-Jun expression and significant suppression of proinflammatory cytokines such as IL-1β, IL-6, and TNF-α." (PMID 33281910, 2020). "Soon after intestinal infection S. enterica induces a significant increase in the expression of IL-17 and related cytokines such as TNF-α, IL-1β, IL-6 and IL-23." (PMID 24340048, 2013). "Furthermore, vascular endothelial B4galnt2 expressing animals (RIII+) exhibited increased Il-6 expression (Z = -1.932, P = 0.0528), but decreased LCN-2 production, suggesting a role for vascular B4galnt2 expression in the host immune response to intestinal infection." (PMID 26133982, 2015).
Lyme disease (17 papers, 2006 to 2025). Lyme disease (named after the towns in the USA where the disease was first identified) is a bacterial infection caused by Borrelia burgdorferi. "Lyme disease has been associated with the proinflammatory cytokines Interleukin-6, Interleukin-8, Interleukin-12, Interleukin-18 and interferon-gamma; the chemokines CXCL12, CXCL13 and CCL19 and increased levels of proinflammatory lipoproteins." (PMID 30149626, 2018). "Elevated levels of IL-6 can cause symptoms of fatigue and malaise, common to many infectious conditions, as well as Lyme disease." (PMID 23866773, 2013). "IL‐6 was the predominant cytokine in skin lesions (“erythema migrans”) of Lyme borreliosis patients and is strongly induced in Borrelia‐stimulated human monocytes in vitro." (PMID 32724523, 2020). "In comparison to the control group, Lyme borreliosis patients presented with higher levels of IL-1β and IL-8, with some extreme outliers in IL-6." (PMID 31366164, 2019). "An increase in levels of innate and Th1-associated cytokines and chemokines, IFN-γ, IL-8, IL-6, and TNF-α has recently been reported in Lyme disease patients." (PMID 30619263, 2018). "Inflammation in Other Chronic Conditions: Lyme disease patients are known to have increased levels of IL-1, IL-6, and TNF-α, also found in chronic fatiguing, musculoskeletal illnesses, and other neurodegenerative disorders." (PMID 30400667, 2018). "Glutathione-mediated detoxification and IL-6 signaling pathways were found to be specific to Lyme disease patients." (PMID 26873097, 2016). "Infection with B. burgdorferi clearly stimulates the coordinated production CRP and SAA along with IL-6 during the acute stage of Lyme disease." (PMID 24740099, 2014). "Among the diseases of the OIND group, neuroborreliosis, Wegener disease, neurosarcoidosis and neurolupus have yielded the highest mean IL-6 levels." (PMID 24015240, 2013). "The concentrations of IL-1β, IL-1Ra, IL-6, sIL-6Rα, sgp130, and IL-15 in the serum of patients with Lyme disease were significantly higher than those in the serum ofcontrol group." (PMID 16864901, 2006). "In contrast, changes in the release of IL-6 and sIL-6Ra afterrhIL-15 stimulation suggest an unfavorable effect of this cytokine leading to enhance IL-6 activity in the course of Lyme disease." (PMID 16864901, 2006). "Unstimulated and rhIL-15-stimulated PMN and PBMC from patients with Lyme disease secreted higher concentrations of IL-6 thancells from healthy control." (PMID 16864901, 2006). "TLR2 expression in relation to expression and production of cytokines and their regulators suggestsa role of this receptor in enhanced IL-6- and inhibition of IL-1β-mediated reactions in patients with Lyme disease." (PMID 16864901, 2006). "IL-6 expression has been shown to be upregulated in patients with acute Lyme disease and remain elevated months after antibiotic treatment, suggesting that increased IL-6 levels in Lyme patients may play a role in the development of chronic symptoms." (PMID 33043033, 2020). "When IL-6 promotor rs1800795 genotypes in Lyme borreliosis patients were addressed according to the group designations of secondary disease phenotypes, we found that especially group 1 (70%) and group 2 (66.7%) had elevated frequencies of heterozygous (G/C) genotypes." (PMID 31366164, 2019). "The current study aimed at the characterization of a cohort of patients with persistent Lyme borreliosis and their inflammatory cytokine phenotype related to the presence and absence of this IL-6 promotor polymorphism." (PMID 31366164, 2019). "While the G variants (G/G and G/C) but not the C variant (C/C) lead to significantly higher IL-6 levels after stimulation with LPS or IL-1 in vitro, one may hypothesize that many inflammatory symptoms in Lyme borreliosis are related to increased IL-6 influenced by its promotor SNP." (PMID 31366164, 2019).
Lyme disease (continued). "IL-6 can play both inflammatory and neurotrophic roles in CNS disorders, and whether it potentiates B. burgdorferi-induced damage or protects neurons in Lyme neuroborreliosis is unknown." (PMID 29922241, 2018). "In contrast, IL-1β has ability to enhance the IL-6 production by immune cells.Furthermore, increased sIL-1RII production by these cells, acting as inhibitor for IL-1β, may lead to decrease its activity in patient with Lyme disease." (PMID 16864901, 2006). "Studies have shown multiple elevated immune markers in both acute Lyme disease (IL-6, IL-8, IL-12, IL-18, IFN-γ, CXCL12, CXCL13) and PTLDS (IL-6, IL-23, IFN-α, CCL19)." (PMID 37760644, 2023). "It is interesting to note increased secretion of IL-6 and its agonist sIL-6Ra by PMN and PBMC after rhIL-15 stimulation leadingto enhance IL-6-mediated response in patients with Lyme disease." (PMID 16864901, 2006). "In the present study, TLR2 expression in relation to expression and production of IL-1β, IL-6, as well as their natural regulators (sIL-1RII, IL-1Ra and sIL-6Rα, sgp130, resp) production by PMN of peripheral blood in patients with Lyme disease were estimated." (PMID 16864901, 2006). "In the present study, TLR2 expression and productionof IL-1β and IL-6 as well as their natural regulators (sIL-1RII, IL-1Ra and sIL-6Rα, sgp130, resp) by PMN of peripheral blood in patients with Lyme disease were examined." (PMID 16864901, 2006).
oral mucositis (17 papers, 2013 to 2025). Inflammation of the mucous membranes of any of the structures in the mouth. "Elevated TNF-α and IL-6 levels have been found in patients with severe radiation-induced oral mucositis as well." (PMID 39519149, 2024). "Among the examined salivary cytokines, IL-6 is the most relevant cytokine for oral mucositis development and severity." (PMID 38792366, 2024). "Elevated levels of the cytokine IL-6 and the chemokine CXCL1, which are also associated with oral mucositis in humans, were found in the murine model after 5-FU treatment and were normalized by H-MW-HA." (PMID 37479691, 2023). "Pertinently, elevated levels of the cytokine IL-6 and the chemokine CXCL1 are also associated with oral mucositis in humans." (PMID 37479691, 2023). "The initiation phase of oral mucositis starts with the damage by reactive oxygen species; then, NF-kB, TNF-α, IL-1β, and IL-6 carry the inflammation phase; immune cells cause the apoptosis of the epithelium and lead to the ulceration phase; eventually, the healing phase occurs." (PMID 37504247, 2023). "In contrast to IL-6 and IL-1β, anti-inflammatory effects in response to radiation exposure were reported for GM-CSF, and a local and systemic administration of GM-CSF showed a potential benefit in the treatment of oral mucositis." (PMID 37384298, 2023). "Pro-inflammatory cytokines such as IL-6 have been related to oral mucositis induced by treatment." (PMID 35954360, 2022). "The primary damage of oral mucositis response describes an activation of transcription factors such as NF-κB leading to the production of pro-inflammatory cytokines such as TNF-α, IL-1β, and IL-6, which cause damage to both epithelium and connective tissue." (PMID 30274314, 2018). "In the present study, the addition of P. gingivalis LPS with 5-FU increased the production of IL-6 and IL-8 from oral mucosal keratinocytes compared with stimulation with 5-FU alone, highlighting the importance of regular oral care in the prevention of chemotherapy-induced oral mucositis." (PMID 37049698, 2023). "TNF-α can modulate the expression of other cytokines such as IL-1β and IL-6 and affect the apoptosis and survival of other cells, hence it was postulated that TNF-α was important in the pathogenesis of oral mucositis." (PMID 36499758, 2022). "All patients with oral mucositis received PBM 6 days/week and the outcome parameters were levels of TNF-α and IL-6 measured before, during, and after administration of PBM." (PMID 32260309, 2020). "Although the mechanisms of chemotherapy-induced oral mucositis remain to be clarified, production of reactive oxygen species and proinflammatory cytokines such as TNF-α and IL-6 in the oral mucosa after exposure to high-dose chemotherapy is considered to be implicated in the pathogenesis." (PMID 27418192, 2016). "Higher concentrations of IL-6 (P<0.001), IL-8 (P = 0.009), and IFN-γ (P = 0.027) as well as lower levels of pro-LL-37 (P = 0.009) were demonstrated in patients that developed oral mucositis compared to those that did not." (PMID 23741421, 2013).
polyarthritis (17 papers, 2016 to 2025). "In A20-deficient mice, elevated production of TNF-α, IL-1β, and IL-6, along with NF-κB hyperactivation, leads to multi-organ autoimmunity and erosive polyarthritis resembling RA." (PMID 41369165, 2025). "Of the three subgroups presented, polyarthritis patients had the highest concentration of serum IL-6 (264.24 pg/mL; IQR 9706.65) and ERA patients the highest concentration of serum IL-10 (30.87 pg/mL; IQR 51.27)." (PMID 39125893, 2024). "Before the era of biological treatment (Il-1 and Il-6 inhibitors), a large proportion of sJIA patients developed severe chronic disease with persistent inflammation and erosive polyarthritis." (PMID 37109756, 2023). "The IL-6-dominant subset has a more severe polyarthritis and higher serum levels of matrix metalloproteinase, whereas the IL-18-dominant subset was more prone to develop MAS." (PMID 34041254, 2021). "To this end, we added tocilizumab, an antibody directed against IL-6 already used in the treatment of polyarthritis, to cell culture medium alone or in combination with ascites." (PMID 29930760, 2018). "The IL-6-dominant subset had a more severe polyarthritis and higher serum levels of matrix metalloproteinase (MMP-3), whereas the IL-18-dominant subset was more prone to develop MAS." (PMID 27999545, 2016). "Inflammatory cytokines such as TNF-α, IL-1β, and IL-6 were major drivers of this polyarthritis." (PMID 34901991, 2022). "Four patients (28.6%) had elevated IL-6 levels (>10.0 pg/mL), with the following clinical features: Skin involvement (dense edema, hyperpigmentation, or depigmentation) and joint impairment (arthralgia or polyarthritis) were observed in all four patients (28.6%) with increased IL-6 levels." (PMID 40843700, 2025). "We found that DNase II−/−STINGS365A/S365A mice, but not DNase II−/−STINGΔCTT/ΔCTT or DNase II−/−STINGL373A/L373A mice, developed polyarthritis characterized by inflammation and bone erosion due to the production of inflammatory cytokines such as TNF-α and IL-6." (PMID 34901991, 2022). "In case of predominant polyarticular arthritis (PA) and in case of lack of response to IL-1 or IL-6 inhibition, TNF-blockers were applied." (PMID 29622022, 2018).
pterygium (17 papers, 2007 to 2025). A wedge-shaped fibrovascular lesion arising from the bulbar conjunctiva and extending to the cornea. "In the complete pterygium group, a clear association was observed between the vascularization index and the area (p = 0.017) and between the IL-6 and VEGF tear film concentrations (p = 0.035)." (PMID 31780873, 2019). "Inflammatory factors, such as interleukin-1, interleukin-6, interleukin-8 and nitric oxide (NO), are upregulated in pterygium." (PMID 41152247, 2025). "Research has indicated that UV radiation can result in genetic alterations impacting the cytokines IL-6 and IL-8 expression in individuals with pterygium." (PMID 38874736, 2024). "Other cytokines (IL-6, IL-8, IL-1β) were detected at similar levels in primary and recurrent pterygium." (PMID 39682531, 2024). "The geometric mean of the IL-6 concentrations of pterygium patients with DE was 8 times higher (95% CI 3.07–20.83) than that of the HCs without DE (p < 0.001) and 4.16 times higher (95% CI 2.30–7.53) than that of the pterygium patients without DE (p < 0.001)." (PMID 33531557, 2021). "Interleukin-6 (IL-6), which is elevated in patients with dry eye disease, was also shown to be significantly higher in cases of recurrent pterygium compared to primary pterygium." (PMID 33975560, 2021). "Emerging evidence has infirmed that infiltration of TGF-β1, VEGF, and IL-6 can promote fibroblast proliferation and vascularization that are involved in the occurrence and development of pterygium." (PMID 31827916, 2019). "UVB has already been described to induce the production of IL-6 and IL-8 in human pterygium epithelial cells, human limbal epithelial cells, human corneal stromal cells, surgically excised pterygia, and whole corneas." (PMID 31780873, 2019). "As inflammation plays a pivotal role in the aetiopathogenesis of pterygium, we aimed to elucidate the outcome of pterygiectomy by investigating the potential of IL-6, IL-8, and VEGF as biomarkers for recovery." (PMID 31780873, 2019). "Anyway, our study provides multiple potential targets, including NLRP3, TGF-β1, VEGF, IL-6, and IL-8, for reducing recurrence of pterygium." (PMID 31827916, 2019). "IL-6 and IL-8 can induce the production of matrix metalloproteinases (MMPs), which are localized to the advancing edges of pterygium." (PMID 23401743, 2013). "Several growth factors such as VEGF and MANF and interleukins such as IL-6 were elevated in pterygium cells exposed to doxycycline." (PMID 22724003, 2012). "By increasing angiogenesis, chronic inflammation, cell proliferation, and invasive capabilities, IL-6 and IL-8 may contribute to pterygium formation." (PMID 41334960, 2025). "Besides pterygium, elevated IL-6 levels are also observed in many common pathological disorders, including corneal angiogenesis, penetrating keratoplasty, and corneal foreign bodies." (PMID 39682531, 2024). "However, differences in tear IL-6 and IL-18 concentrations were insignificant between the HCs and pterygium patients (p = 0.371 and p = 0.727, respectively)." (PMID 33531557, 2021). "Thus, we believe that VEGF is a contributing factor in the pterygium pathogenesis, whereas the roles of IL-6 and IL-18 remain inconclusive." (PMID 33531557, 2021). "Nevertheless, whether high expression of TGF-β1, VEGF, IL-6, and IL-8 can also promote the recurrence of pterygium is seldom reported." (PMID 31827916, 2019). "Moreover, reduced expression of TGF-β1, VEGF, and IL-6 in pterygium tissues was also confirmed after MMC administration." (PMID 31827916, 2019). "Further substantiating our hypothesis of an enhanced tear film cytokine production are the increased IL-6 levels found in reflex tears of pterygium patients." (PMID 31780873, 2019). "UV-mediated genetic trauma may affect the expression of cytokines, such as interleukin (IL)-6 and IL-8, in patients with pterygium." (PMID 23401743, 2013).